CAT (catalase)
Diseases named in the same sentence as CAT in open-access papers (continued):
Sharing a sentence is not in itself a finding about the gene and the disease.
hyperthyroidism (14 papers, 2012 to 2025). Overactivity of the thyroid gland resulting in overproduction of thyroid hormone and increased metabolic rate. "A decrease in SOD levels and increase in CAT activity due to hyperthyroidism observed in this study may be owing to hyperthyroidism causing superoxide accumulation, which induces oxidative stress and prevents follicle development." (PMID 40610792, 2025). "Similarly, the decrease in SOD levels and increase in CAT activity observed in hyperthyroid animals may show that hyperthyroidism causes oxidative stress by disrupting the antioxidant balance in tissues." (PMID 40610792, 2025). "To summarize, the SOD and CAT activity values in this study show that hyperthyroidism induces oxidative stress, which disrupts the hormonal balance of the body and causes ovarian damage." (PMID 40610792, 2025). "Serum oxidant (MDA and NO) and antioxidant (GSH, SOD, GPx and CAT) markers of healthy and hyperthyroidism treated animals’ groups as compared to control group." (PMID 37020549, 2023). "The increase in ROS production mediated by hyperthyroidism was correlated with an increase in the genomic expression of the antioxidant enzymes CAT and GPx-1 in lymphoid cells of lymph nodes and spleen, evaluated by conventional PCR and real-time PCR." (PMID 31281590, 2019). "In another study, it has been suggested that hyperthyroidism had an impact on uterine oxidative stress owing to alterations of the total superoxide dismutase, catalase and glutathione peroxidase activities in utero, thus influencing fertility." (PMID 31729993, 2019). "In a rat model of hyperthyroidism, catalase liver activity, GPx, and lipid peroxidation were all increased suggesting that increased oxidative damage, as observed in G2, can induce increases of antioxidants enzymes activity to control the imbalance." (PMID 30462808, 2018). "MOK acupuncture significantly increased hepatic GSH levels and decreased the expression of SOD and catalase in the liver, heart, and brain tissues of hyperthyroidism rats." (PMID 29246135, 2017). "SOD levels (p < 0.05) and CAT levels (p < 0.001) were all significantly decreased in the hyperthyroidism model group compared to the normal group, while EEP-L (p < 0.001), EEP-M (p < 0.001), and EEP-H (p < 0.001) were found to significantly increase SOD levels and CAT levels in hyperthyroid mice." (PMID 36613632, 2022). "In conclusion, it is important to emphasize the fact of a tissue-linked variability in the effects of hyperthyroidism on the activity of antioxidant enzymes (Mn-superoxide dismutase (SOD) or Cu,Zn-SOD, catalase (CAT), glutathione-peroxidase) with differential effects of the two thyroid hormones." (PMID 24351864, 2013). "Hyperthyroidism has many effects on cholesterol, triglyceride, lipid, oxidation, antioxidants, malondialdehyde (MDA), catalyst enzyme catalase (CAT), liver enzymes, uric acid, urea, creatinine, and histopathological changes in the liver and kidney." (PMID 33754657, 2021). "Hyper-thyroidism upregulated the activities of SOD and GR while the activities of CAT and GPx were down regulated." (PMID 31092832, 2019). "Furthermore, the effects of hyperthyroidism on antioxidant enzyme activity, including Mn-, Cu-, or Zn-superoxide dismutase (SOD), CAT, and GPx, vary by tissue type, with T3 and T4 exerting distinct influences depending on the tissue analyzed." (PMID 40429666, 2025). "The results of the current study showed that hesperidin post-treatment of hyperthyroidism rats reduced the MDA level, and created a substantial increase in CAT, GPx, and SOD activities as well as GSH level compared to their values of the untreated hyperthyroidism modeled group." (PMID 37020549, 2023). "Next, the expression of CAT was increased in the hyperthyroidism group, but this was decreased by treatment with MOK pharmacopuncture in the liver, brain, and heart of hyperthyroidism rats." (PMID 29246135, 2017).
hyperthyroidism (continued). "Co-administration of vitamin E and curcumin improved the activities of enzymatic antioxidant including cytosolic catalase, cytosolic glutathione peroxidase-1 (GPx1), mitochondrial SOD2 and glutathione reductase, and normalized GPx1 protein expression in l-thyroxine-induced hyperthyroidism in rat." (PMID 24674233, 2014).
liver diseases (14 papers, 2014 to 2025). "Loss of CAT activity is an important part of liver diseases and is usually accompanied with H2O2 accumulation rather than oxygen generation, thereby further promoting the liver hypoxia and OS18,19." (PMID 36797395, 2023). "In another study conducted with male and female groups to determine the oxidative stress level in patients with liver disease, CAT and SOD activity were found above the upper decision line in both men and women." (PMID 35720997, 2022). "The imbalance of endogenous enzymes including glutathione (GSH), superoxide dismutase (SOD), and catalase (CAT) is an important pathogenesis of liver diseases, which could be reflected by aberrant expression of antioxidant signaling such as Nrf2/HO-1 pathway." (PMID 31080480, 2019). "Together, catalase expression in HCC patients can be clinically useful for prediction of patient survival, and restoration of catalase expression in HCCs could be an important strategy for intervention in HBV-induced liver diseases." (PMID 25361011, 2014). "It has been suggested that an insufficient antioxidant defense system composed of antioxidant enzymes, including catalase (CAT) and nonenzymatic molecules, is a key factor triggering oxidative damage in the progression of liver disease." (PMID 37759451, 2023).
lymphoma (14 papers, 1983 to 2025). A malignant (clonal) proliferation of B- lymphocytes or T- lymphocytes which involves the lymph nodes, bone marrow and/or extranodal sites. "Prior research has demonstrated that induction of DMBA-lymphoma causes a noteworthy drop in TAC, GPx, GST, GR, Catalase, and SOD activity, as well as a notable increase in MDA." (PMID 40126665, 2025). "In the present study, the advantages of ROS triggering TF cascade targeted effect and catalase improving hypoxia microenvironment ability were utilized to enhance vPDT treatment on malignant lymphoma." (PMID 33240803, 2020). "Synthetic Pt nanoparticles have been shown to scavenge ROS in cultured HeLa cells, to induce expression of antioxidant enzyme genes in rat skeletal muscle L6 cells, and to act as an SOD/catalase mimetic agent in human lymphoma cells." (PMID 25029447, 2014). "It is noteworthy that similar changes are found in mitochondria from lymphoma cells made resistant to oxidative stress by different approaches (catalase transfection and selection by hydrogen peroxide treatment)." (PMID 22949856, 2012). "The lymphoma model system consists of the WEHI7.2 murine thymic lymphoma-derived cell line and variants established by transfection of these cells with catalase (CAT2, CAT38) or by gradual selection for growth in the presence of hydrogen peroxide (200R)." (PMID 22949856, 2012). "Coexposure of lymphoma HS-sultan cells to catalase completely prevented EGCG-induced apoptosis; downregulation of the antiapoptotic-associated proteins, Bcl-2 and Mcl-1, and of procaspase-3 after EGCG treatment was prevented by catalase pretreatment." (PMID 21776260, 2011). "In this study, we designed a lymphoma tissue factor-targeted “O2-evolving” strategy combining PDT with catalase and HMME-encapsulated, EGFP-EGF1-modified PEG-PLGA nanoparticles (CENPs) to boost PDT efficiency; this combination takes advantage of the low oxygen tension of lymphoma." (PMID 33240803, 2020). "Similarly PC6, P388, TLX5 lymphoma and MB showed lower catalase activity than the corresponding normal tissues." (PMID 6860548, 1983). "SOD, Catalase, GPx, GST, GR, and TAC levels were significantly lower in the untreated control DMBA-lymphoma-induced animals than in the normal control mice." (PMID 40126665, 2025). "We first constructed a TF-cascade-targeted “O2-evolving” system—catalase and HMME-encapsulated, EGFP-EGF1-modified PEG-PLGA nanoparticles (CENPs)—to target malignant lymphoma vessels." (PMID 33240803, 2020). "The main finding of this study is that by reproducing in vitro a condition of in vivo hyperCHO, lymphoma lymphoblastic cells overexpressed genes for antioxidant proteins (SOD1, SOD2, CCS, GSR, GSS and CAT) with the only exception of GRX2." (PMID 26754536, 2016). "Oral administration of the A. paniculata aqueous extract significantly enhanced CAT, SOD and GST activities in the liver of lymphoma bearing mice." (PMID 20465823, 2010). "In contrast to what we see in RIIβ mice, we have reported that long-lived mitochondrially targeted catalase transgenic mice do not suppress lymphosarcoma but do attenuate epithelial cancers." (PMID 19536287, 2009). "In addition, both DMBA-lymphoma-induced animal groups treated with ultrasound, laser, or ultrasound and laser combination alone manifested a significant decline in TAC levels and in the SOD, Catalase, GPx, GST, and GR activities regarding to the mice healthy control group." (PMID 40126665, 2025). "Compared to the untreated DMBA-lymphoma-induced control mice, activated CPL-Micelles in the IRL, US, and combination of IRL and US groups demonstrated a considerable elevation in the SOD, Catalase, GPx, GST, and GR, activities and TAC level while not approaching the level of normal control group." (PMID 40126665, 2025).
osteoporosis (14 papers, 2012 to 2025). A condition of reduced bone mass, with decreased cortical thickness and a decrease in the number and size of the trabeculae of cancellous bone (but normal chemical composition), resulting in increased fracture incidence. "Hence, CAT polymorphisms linked to osteoporosis remain controversial, making it necessary to increase the study sample and explore its functional implication with BMD variation." (PMID 37107290, 2023). "Additionally, oxidative stress markers -such as elevated levels of malondialdehyde, advanced oxidation protein products and vitamin B12, along with reduced antioxidants like catalase, glutathione peroxidase, uric acid and folate-have been significantly associated with osteoporosis." (PMID 40018266, 2025). "For instance, B. adolescentis has been shown to regulate catalase activity and host metabolism, improve osteoporosis and neurodegeneration in a mouse model of premature aging, and increase both health span and lifespan in C. elegans." (PMID 41472063, 2025). "In this study, MAD level decreased, SOD, GPX and CAT activities increased after CS treatment, indicated that CS has antioxidative stress ability, and it was one of reasons that CS exerts antidiabetic osteoporosis effect." (PMID 32722636, 2020). "Additionally, in case of postmenopausal women with osteoporosis, CAT activity was found to be lowered." (PMID 25485304, 2014). "Finally, nicotine heightens inflammation, disrupts the body’s oxidative-antioxidant balance, elevates malondialdehyde levels, and decreases superoxide dismutase and catalase levels, all of which may contribute to osteoporosis." (PMID 36817605, 2023). "In this study WGE increased SOD, CAT, and GSH activities and inhibited the level of MDA in lipid peroxidation products; that is, it relieved osteoporosis in DM rats through antioxidant pathways." (PMID 40529421, 2025). "The analyzed polymorphisms belonging to a wide variety of genes, e.g., SOD, PON, GPx, GST, TXN, CAT, ALOX12, GSR, and NOS, focused on BMD variation, which is the current clinical gold standard for analyzing reductions in bone mass and diagnosing osteoporosis." (PMID 37107290, 2023). "It has been demonstrated that circulating levels of catalase, superoxide dismutase 2 (SOD 2) and peroxiredoxin 2 (PRX2) are lower in postmenopausal women with osteoporosis than health controls." (PMID 35387349, 2022). "It is also interesting that women with osteopenia had lower levels of catalase, SOD2, and PRX2 than those with osteoporosis." (PMID 31452599, 2019).
skin cancer (14 papers, 2015 to 2024). "Fisetin has significant effect on production of free fatty acids, tumor incidence, IL‐1α, TNF‐α, and antioxidant enzymes (glutathione and catalase contents) in ultravoilet‐induced skin cancer rats." (PMID 33473265, 2021). "Ultraviolet radiation (UVR) increases oxidative stress not only by upregulating nitric oxide synthase (NOS) synthesis but also by impeding catalase (CAT) to scavenge hydrogen peroxide, thus leading to increased risk of sunburn, photoaging and skin cancer." (PMID 33754031, 2021). "Stigmasterol inhibited the growth of skin carcinoma through elevated levels of antioxidative enzymes (glutathione, catalase, and superoxide dismutase) and reduced lipid oxidation and DNA damage." (PMID 28846663, 2017). "A systematic review of gene–sun exposure interactions in skin cancer identified variants of MC1R, CAT, and NOS1 that could help explain the mechanism by which sun exposure causes CM." (PMID 39281383, 2024). "Similarly, CAT downregulation has been reported during skin cancer progression." (PMID 34943091, 2021). "Regarding skin cancer, interesting disparities emerge in the expression profiles of key antioxidant enzymes, such as copper–zinc SOD, manganese SOD, and CAT, as well as the lipid peroxidation product marker protein-bound malondialdehyde." (PMID 39456749, 2024). "Strikingly, pre-treatment of both cell types with catalase abrogated cell death induction in GSH + PEF combined treatments to baseline levels, ultimately leading to a significantly reduced cytotoxicity in A375 and A431 skin cancer cells." (PMID 36499100, 2022). "Furthermore, by maintaining glutathione, catalase, SOD, and GSH peroxidase activity through the Nrf2–antioxidant response, PTS showed anti-cancer activity in a UVB-stimulated skin cancer model." (PMID 36234852, 2022). "Similarly, in rodent models of UVB-induced skin cancer, the anti-cancer activity of PTS was observed to include the prominent induction of Nrf2-mediated antioxidant signaling, resulting in glutathione level maintenance and the improved activities of catalase, SOD, and GPX." (PMID 36234852, 2022).
varicocele (14 papers, 2019 to 2024). A condition characterized by the dilated tortuous veins of the spermatic cord with a marked left-sided predominance. "The induction of varicocele was associated with oxidative stress, characterized by the significant decrease (in the left testis) (p<0.01) of catalase and SOD activities, and elevated lipid peroxidation." (PMID 33667053, 2021). "Meanwhile, compared to control group, GSH, T-SOD, and CAT levels were reduced in the bilateral varicocele group (p < 0.05)." (PMID 36819092, 2023). "T-SOD levels in patients with bilateral varicocele were decreased by ∼33% (p < 0.01); CAT levels in patients with bilateral varicocele were decreased by ∼95% (p < 0.01)." (PMID 36819092, 2023). "In the present study, varicocele was associated with a significant increase in MDA concentration, but with low SOD and catalase activities." (PMID 33667053, 2021). "The imbalance marked by increased MDA and decreased SOD and catalase activities due to varicocele was reversed by D. arborea extracts, with the highest effects observed in rats administered with the aqueous extract (500 mg/kg)." (PMID 33667053, 2021). "CAT activity was augmented in both the leukocytospermia and varicocele groups (P = 0.0001)vs. controls." (PMID 31781347, 2019). "Both the leukocytospermia and varicocele groups showed increased values of CAT activities (P < 0.001) than controls." (PMID 31772701, 2019). "Moreover, treatment with G. bimaculatus significantly restored the increased levels of MDA, ROS, and reactive nitrogen species (RNS) and the reduced levels of SOD, GPx, and CAT in testicular tissue of Sprague–Dawley rats affected by varicocele." (PMID 33718423, 2021). "Additionally, a clinical study demonstrated that Jingling, a substance derived from a Chinese plant, increases catalase activity and prevents oxidative stress in men with varicocele." (PMID 33667053, 2021). "Finally, CAT activity was higher in both the leukocytospermia and varicocele groups (P = 0.0001) than that measured in the control group." (PMID 31781347, 2019). "Our results clearly showed that lipid peroxidation, total antioxidant capacity, the level of catalase, and SOD improved in varicocele‐treated rats with lycopene especially at a dose of 10 mg/kg." (PMID 34925809, 2021). "In the lycopene group (10 mg/kg), sperm concentration, the levels of TAC, and catalase (CAT) activity were improved so the levels of ROS, MDA, and %DNA damage were reduced compared with varicocele group." (PMID 34925809, 2021). "In the left testis, the aqueous and ethanolic extracts of D. arborea significantly increased (p<0.05) catalase activity, but decreased MDA levels, compared with untreated varicocele animals." (PMID 33667053, 2021). "In this research, we confirmed that leukocytospermia and varicocele are characterized by an impairment of redox status because the GSH/GSSG ratio was decreased and negatively correlated with cytokines, MDA, and CAT." (PMID 31781347, 2019). "Animals with 3 weeks of varicocele showed a significant (p < 0.05–0.001) decrease in body and sex organ weights, total proteins, sperm characteristics, testosterone concentration, SOD, catalase, and total peroxidase activities." (PMID 34567203, 2021). "Interestingly, the results revealed that the administration of lycopene in the varicocele group, especially at a dose of 10 mg/kg, reduced the ROS levels by increasing both TAC levels and CAT enzyme activity." (PMID 34925809, 2021). "This hypothesis is supported by the positive correlation observed between catalase activity and MDA concentrations in men with varicoceles." (PMID 32899311, 2020).